VIM (vimentin)
Diseases named in the same sentence as VIM in open-access papers (continued):
Sharing a sentence is not in itself a finding about the gene and the disease.
gallbladder tumor (2 papers, 2016 to 2021). "For vimentin, the expression was highest in intrahepatic tumors, whereas in perihilar and gallbladder tumors, the expression was lowest (p < 0.05)." (PMID 27941621, 2016). "Similarly in gallbladder tumor cells, fibrinogen can promote migration and metastasis by increasing the expression of vimentin, decreasing the expression of E-cadherin, and promoting the process of epithelial-mesenchymal transition (EMT)." (PMID 33995485, 2021).
giant cell carcinoma (2 papers, 2022 to 2023). "The giant cell carcinoma specimens were positive for both CK7 and Vimentin, and comprised entirely of polymorphic mononuclear and/or multinuclear neoplastic giant cells." (PMID 36447228, 2022).
gliosarcoma (2 papers, 2017 to 2022). A rare histological variant of glioblastoma (WHO grade IV) characterized by a biphasic tissue pattern with alternating areas displaying glial and mesenchymal differentiation (WHO). "The reaction to vimentin is more associated with the mesenchymal component of gliosarcoma, but can also be identified in giant cell glioblastoma, its role having implications in proliferation and invasiveness." (PMID 36005160, 2022). "Gliosarcomas were excluded according to established histologic and immunohistological criteria (GFAP, vimentin and reticulin staining)." (PMID 28881571, 2017).
glomerular disease (2 papers, 2012 to 2016). "Vimentin mutations in familial or sporadic forms of glomerular disease have not been reported." (PMID 27942003, 2016).
granular cell tumor (2 papers, 2009 to 2017). An unusual benign or malignant neoplasm characterized by the presence of neoplastic large polygonal cells with granular, eosinophilic cytoplasm which contains abundant lysosomes. "Strong staining of S-100 protein, CD68, vimentin, E-cadherin and low proliferative activity observed with Ki-67 expression confirmed the diagnosis of a granular cell tumor." (PMID 28057062, 2017). "The granular cell tumor was immunohistochemically positive for vimentin, S100 protein, and neuron-specific enolase." (PMID 27956961, 2009). "The granular cell tumors were immunohistochemically positive for vimentin, S100 protein, and neuron-specific enolase, and negative for cytokeratins and other antigens examined." (PMID 27956961, 2009).
Hematuria (2 papers, 2019 to 2021). The presence of blood in the urine. "In control 5/6 NE rats that had mild hematuria, <10% of the tubules expressed vimentin (mesenchymal marker), whereas in 5/6 NE rats that were treated with warfarin and had moderate chronic hematuria, over 30% of the tubules expressed vimentin in tubular epithelial cells." (PMID 34901065, 2021).
hypercholesterolaemia (2 papers, 2017 to 2022). "Persistent hypercholesterolaemia was responsible for diffused effacement or further cytoskeletal re‐assembly that was associated with podocyte malfunction, as demonstrated by mutations of SD proteins and increased vimentin and mmp9 expression, and resultant proteinuria." (PMID 27704688, 2017).
hypospadias (2 papers, 2024). Hypospadias is the displacement of the urethral meatus on the ventrum of the penis. "Compared with normal foreskin, we observed reduced expression of SOX9, Wnt/β‐catenin pathway signaling and mesenchymal markers Vimentin and α‐SMA in hypospadias tissue." (PMID 40626133, 2024).
IgA nephropathy (2 papers, 2014 to 2023). "Compared with the kidney control group, the expression of vimentin on the glomerulus and renal tubule of the IgA nephropathy group were both significantly increased." (PMID 37170272, 2023). "In the present study, it was observed that α-SMA and vimentin were expressed in renal tubular epithelial cells of IgA nephropathy renal biopsies." (PMID 24788122, 2014). "In IgA nephropathy tissue, vimentin levels were higher in the glomerulus and expressed in renal tubular epithelial and interstitial cells." (PMID 24788122, 2014). "Certainly, the detection of α-SMA and vimentin may be used as one of the clinical indicators in the assessment of IgA nephropathy prognosis." (PMID 24788122, 2014). "α-SMA, vimentin and the apoptotic index may be used as important markers for evaluating the prognosis of IgA nephropathy." (PMID 24788122, 2014). "The present study demonstrated that α-SMA and vimentin expression of tubule epithelial cells, interstitial MF accumulation, collagen deposition, apoptosis of tubular epithelial and interstitial cells, interstitial fibrosis and renal dysfunction have a significant relevance in IgA nephropathy." (PMID 24788122, 2014). "In this study, CD31, α-SMA, and vimentin were selected as markers of EndMT, and the expression of CD31 in the glomerulus of children with IgA nephropathy was significantly decreased, while the expression of α-SMA and vimentin was significantly increased." (PMID 37170272, 2023). "Among IgA nephropathy with different pathological grades, with the development of the disease, tubulointerstitial α-SMA and vimentin expression gradually increased (P<0.05 or P<0.01)." (PMID 24788122, 2014). "Therefore, the transdifferentiation and apoptosis of renal tubular epithelial cells reflected the clinical severity of IgA nephropathy, and the detection of the expression of α-SMA, vimentin and apoptosis may be useful as an important index for evaluating the prognosis of IgA nephropathy." (PMID 24788122, 2014).
infarction (2 papers, 2018 to 2024). A localised pathological necrosis of tissue resulting from obstruction of the blood supply usually by a thrombus, an embolus, or vascular torsion. "The same authors also suggested that positivity for vimentin usually indicates the presence of remodeling processes following infarction, ischemia and necrosis." (PMID 39682376, 2024). "In vimentin-positive mesenchymal cells the proliferation was most dynamic and mesenchymal cell density augmented in the peri-infarction area of all MI groups at 24 h after MI." (PMID 29752300, 2018).
intimal sarcoma (2 papers, 2014 to 2019). A malignant neoplasm arising from the large blood vessels. "Vimentin is frequently positive in intimal sarcoma, whereas vascular markers such as CD31, CD34, vWF, and smooth muscle cell markers such as desmin are usually negative." (PMID 30925179, 2019).
invasive lobular carcinoma (2 papers, 2017 to 2020). "The vimentin-positive cells at the invasion front were arranged in thin rows of individual cells interspersed between stromal (S) connective tissue (blue arrow), typical of the invasive lobular carcinoma that lacks E-cadherin." (PMID 28750639, 2017).
keratoconus (2 papers, 2016). A degenerative, structural disorder of the eye, characterized by a cone-shaped protrusion of the cornea. "Decentralized expression of FAP and vimentin was visible throughout the corneas of the patients with keratoconus, and in the superficial stroma, excessive expression of FAP and vimentin was observed." (PMID 26885515, 2016). "The expression of stromal proteins such as vimentin, decorin and keratocan was reported to increase following keratoconus surgery." (PMID 27473120, 2016). "Eight keratoconic corneal buttons harvested from the 8 advanced keratoconus patients with superficial stromal scarring underwent immunohistochemistry staining, and the scar regions expressed high immunogenicity of fibroblast activation proteins (FAP), vimentin, and α-smooth muscle actin (α-SMA)." (PMID 26885515, 2016).
kidney stone (2 papers, 2017 to 2023). "Genes encoding for Runx1, Runx2, KRT 18, KRT 8, VIM, Fn-1, Col1a1 and Col1a2 were up regulated during hyperoxaluric conditions and further increased after crystal deposition or nephrolithiasis." (PMID 29091707, 2017). "We found that ethylene glycol-induced kidney stone rats had reduced E-cadherin expression and increased vimentin and α-SMA expression compared with control rats." (PMID 37569334, 2023). "In addition, expression of the epithelial marker E-cadherin was increased, mesenchymal markers α-SMA and vimentin decreased, and fibronectin and collagen 1 expression levels were relatively lower in the yellow tea gavage nephrolithiasis rat model group." (PMID 37569334, 2023).
Krabbe disease (2 papers, 2017 to 2022). A lysosomal disorder that affects the white matter of the central and peripheral nervous systems. "iPSCs from three healthy controls and two donors with infantile onset Krabbe disease successfully differentiated into astrocytes that expressed appropriate lineage markers vimentin, S100β, CD44, and GLAST." (PMID 35921286, 2022). "Importantly, DEDA attenuated the psychosine-induced decrease in expression of MBP and MOG as well as vimentin supporting the idea that astrocyte function as well as oligodendrocyte myelination state is altered in Krabbe disease." (PMID 29095858, 2017).
large cell carcinoma of the lung (2 papers, 2008 to 2024). "Interestingly, it was reported that large cell carcinoma of the lung is often vimentin-positive, and our case was also vimentin-positive." (PMID 18588705, 2008). "Based on 2015 WHO classification criteria in redefining large cell lung carcinoma, the expression of specific markers (TTF1, Napsin A, P 40, CK5/6, CK, vimentin and ZEB1) is analyzed by immunohistochemistry." (PMID 39064008, 2024).
leukoplakia (2 papers, 2022). A white patch or plaque on a mucous membrane that cannot be characterized clinically or pathologically as any other disease. "Our group has also reported aberrant vimentin expression in premalignant oral lesions, such as leukoplakia and submucous fibrotic (SMF) tissues, as well as primary keratinocyte cultures isolated from these tissues." (PMID 35207438, 2022). "As a third step, we wanted to evaluate the significance of vimentin in oral premalignant lesions that would comprise of leukoplakia, OSMF as well as buccal cancers." (PMID 35498535, 2022). "ELISA for vimentin was attempted to evaluate the secretion of vimentin in saliva samples from normal healthy volunteers compared with patients presenting oral leukoplakia, oral submucous fibrosis (OSMF), and OSCC." (PMID 35498535, 2022). "Previous studies have shown that vimentin expression in lesions of leukoplakia and submucous fibrosis could be an early event in tobacco and areca nut associated tumorigenesis process." (PMID 35498535, 2022). "In addition, analysis of leukoplakia and OSCC epithelial tissue samples also revealed high vimentin and low E-cadherin expression." (PMID 35207438, 2022). "Interestingly, the percentage of vimentin-positive lesions was higher in clinically non-homogenous leukoplakia than in homogeneous leukoplakia." (PMID 35207438, 2022).
Leydig cell tumor (2 papers, 2012 to 2013). A sex cord-stromal tumor occurring in the testis and rarely in the ovary. "The immunological stain was positive for actin and vimentin, markers for mesenchymatous tissue, as well as for inhibin, a marker for cells of stroma or sexual cord tumors, which could indicate a Leydig cell tumor." (PMID 23388220, 2013). "Among the Sertoli-Leydig cell tumors group, the expression of Inhibin, Vimentin and Pancytokeratin overlapped that of the JGCT group, with a strong positivity for Inhibin (5/6) and Vimentin (5/6)." (PMID 23029311, 2012).
liver cirrhosis (2 papers, 2019 to 2023). "In summary, we found ACTB, TAGLN, VIM and SOX9 are the potential key biomarkers of liver cirrhosis." (PMID 36725885, 2023).
liver steatosis (2 papers, 2024). "Exosomes from R patients, those exhibiting a clinical improvement of liver steatosis, were found to decrease α-SMA, COL1A1, Vimentin, and EGFR expressions by LX-2 cells (stellate cells), leading to a decrease in the extracellular matrix (ECM) protein deposition and fibrosis." (PMID 38338770, 2024).
Löfgren’s syndrome (2 papers, 2018 to 2022). "A pronounced response of T-cells of the bronchoalveolar fluid to vimentin and citrullinated vimentin was also demonstrated in patients with the HLA genotype DR-B1*0301 and acute forms of the disease, which was confirmed in patients with Löfgren’s syndrome in our study." (PMID 36010289, 2022).
Lung Injury (2 papers, 2021 to 2023). "It was postulated that vimentin is essential for the assembly and NLRP3 inflammasome activation and leads to elevation in active IL-1β that participate in lung injuries in rodent models." (PMID 33995030, 2021).
lymphoid neoplasm (2 papers, 2019 to 2021). A neoplasm composed of a lymphocytic cell population which is usually malignant (clonal) by molecular genetic and/or immunophenotypic analysis. "Additionally, and since ST2 immunoreactivity coincides with a decrease of E-cadherin in metastatic lymphoid tumor cell membrane, we evaluated the effect of IL-33 on the transcript levels of classical EMT markers (E-cadherin, N-cadherin and vimentin)." (PMID 31281317, 2019).
malaria (2 papers, 2024 to 2025). Malaria is a serious and sometimes fatal disease caused by a parasite that commonly infects a certain type of mosquito which feeds on humans. "Infections with Plasmodium, the parasite responsible for malaria, can also affect the expression and function of vimentin." (PMID 39997396, 2025). "Similar to tubulin filaments, only shrinkage of vimentin filaments and ECs, and presence of eccentric nuclei were observed in vimentin filaments induced by malaria sera." (PMID 38183117, 2024). "The work investigated the cytoskeletal changes (microfilaments-actin, microtubules-tubulin and intermediate filaments-vimentin) in ECs induced by malaria sera (Plasmodium vivax, uncomplicated P. falciparum and complicated P. falciparum), in relation to the levels of pro-inflammatory cytokines." (PMID 38183117, 2024). "The results of increase immunofluorescence intensities of cytoskeleton (F-actin, F:G actin ratio, tubulin and vimentin filaments) in ECs stimulated with sera from complication P. falciparum malaria could be further investigated for possible prognostic factor for malaria severity." (PMID 38183117, 2024).
mastitis (2 papers, 2019 to 2022). Inflammation of breast tissue during lactation or postpartum due to an obstructed duct or infection. "In view of these results, it will be interesting to further investigate on the role of vimentin in mastitis, as already done in other inflammatory conditions." (PMID 31676851, 2019).
Meningeal Melanocytoma (2 papers, 2010 to 2012). A usually well differentiated melanocytic neoplasm arising from the meninges. "Immunohistochemically, meningeal melanocytomas show positive cytoplasmic reactivity for S100 protein and vimentin." (PMID 21264144, 2010). "Immunohistochemically, meningeal melanocytomas are positive for S-100 protein, HMB-45 and vimentin." (PMID 22759717, 2012).
metaplastic breast carcinoma (2 papers, 2013 to 2024). A group of invasive breast carcinomas characterized by the presence of an adenocarcinomatous component which is admixed with a dominant component that is composed of squamous cells, spindle cells, or mesenchymal cells. "Microdissected metaplastic breast carcinoma has been shown to have a specific loss of miR-200 which correlates with increased expression of vimentin and decreased E-cadherin in the mesenchymal component." (PMID 23950995, 2013).
myelogenous leukemia (2 papers, 2015 to 2025). "In principal, our data suggest that dramatically increased expression level of vimentin in doxorubicin-resistant myelogenous leukemia cells contributes to the resistance to cytotoxic agent to some extent." (PMID 25628518, 2015).
myxoid liposarcoma (2 papers, 2012 to 2018). A liposarcoma characterized by the presence of round non-lipogenic primitive mesenchymal cells and small signet ring lipoblasts within a myxoid stoma with a branching vascular pattern. "Pulmonary myxoid liposarcoma is multinodular-architecture in myxoid stroma with Vimentin and S-100 positive which is similar to EMC, however, lack of lipoblasts and plexiform capillary network exclude the diagnosis." (PMID 22925697, 2012).
neuropathies (2 papers, 2016 to 2022). "Our data showing the induction of Cdc2 and phospho-vimentin levels by BGJTD suggest possible molecular basis on how BGJTD acts on neuropathy." (PMID 27770785, 2016).
Oropharyngeal Squamous Cell Carcinoma (2 papers, 2022 to 2025). "In addition, cell membrane β-catenin expression was significantly associated with vimentin in HPV-associated oropharyngeal squamous cell carcinoma." (PMID 35207438, 2022). "Tissue blocks of biopsy-proven Oropharyngeal Squamous Cell Carcinoma were subjected to Immunohistochemistry (IHC) for evaluating the expression of p16, e-cadherin, vimentin and podoplanin." (PMID 41146851, 2025). "In 202 oropharyngeal squamous cell carcinoma (OPSCC) patients, vimentin expression was found in tumor-associated stromal cells." (PMID 35207438, 2022).
ovarian adenocarcinoma (2 papers, 2018 to 2019). An adenocarcinoma that arises from the ovary. "Human ovary adenocarcinoma SCOV3 cells were used as positive control for Ki-67 and Vimentin and MCF-7 were used as Vimentin−/Ki-67high cells." (PMID 30858763, 2019). "NIH:OVCAR3 (ovarian adenocarcinoma) and HT29 (colorectal adenocarcinoma) cells with high TTP levels exhibited high E-cadherin, low N-cadherin, and low vimentin, whereas low TTP-expressing SKOV3 (ovarian adenocarcinoma) and H1299 (non-small lung carcinoma) cells displayed low E-cadherin expression." (PMID 30380668, 2018).
ovarian endometriosis (2 papers, 2019 to 2025). A non-neoplastic disorder characterized by the growth of endometrial tissue in the ovaries. "Collectively, these phenomena indicated that EMT occurs during ovarian endometriosis, which mainly owing to down‐regulated E‐cadherin and up‐regulated vimentin." (PMID 31560827, 2019). "Elevated vimentin expression in ovarian endometriosis was also reported by previous studies." (PMID 40135061, 2025).
ovarian serous cystadenocarcinoma (2 papers, 2020 to 2022). A malignant serous cystic epithelial neoplasm arising from the ovary. "The positive correlation between HK2 and CDH2, fibronectin, MMP9, ZEB1, ZEB2 and vimentin in OV (ovarian serous cystadenocarcinoma) was confirmed by using TIMER 2.0." (PMID 35953860, 2022). "In addition, we analyzed the association of L1CAM, vimentin and TGF-β1 expression with the overall survival (Kaplan Meier Plot) from a data set of 300 ovarian serous cystadenocarcinoma tumor samples (The Cancer Genom Atlas, TCGA RNAseq expression, Pan-Cancer Atlas)." (PMID 31952346, 2020).
papillary adenoma (2 papers, 2014 to 2025). An adenoma characterized by the presence of papillary epithelial patterns. "The ERa-/PR- intraductal papillary adenoma had adjacent non-neoplastic tissue that was also ERa-/PR- and 100% of the luminal neoplastic cells were VIM + in this case." (PMID 25249140, 2014).
parasite infection (2 papers, 2015 to 2020). "In contrast, fibronectin, vimentin and collagen type IV were also investigated as a part of the ECM components susceptible to parasite infection." (PMID 32552750, 2020). "Taken together, the present study reinforces previous results from our group implicating the gp85 superfamily of glycoproteins and the intermediate filament proteins cytokeratin and vimentin in the parasite infection process." (PMID 26398185, 2015).
peritoneal (2 papers, 2018 to 2024). "The trend of changes in levels of SIRT6, E-cadherin, vimentin, and TGF-β1 indicates that prolonged dialysis time and a history of peritonitis lead to a decrease in SIRT6 and changes in MMT in peritoneal mesothelial cells." (PMID 38483736, 2024). "Compared with the group without a history of peritonitis, the protein and gene levels of vimentin and TGF-β1 in the group with a history of peritonitis were significantly increased, while the protein and gene expression levels of SIRT6 and E-cadherin were significantly reduced (P < 0.05)." (PMID 38483736, 2024).